MACC1 (MET transcriptional regulator MACC1)
Diseases named in the same sentence as MACC1 in open-access papers (continued):
Sharing a sentence is not in itself a finding about the gene and the disease.
breast carcinoma (continued). "By using two large cohorts of breast cancer cases, we have found that the level of MACC-1 significantly correlates with the clinical staging and tumor-node-metastasis (TNM) classification of the disease." (PMID 23497677, 2013). "Statistical analysis showed a significant correlation of MACC1 expression with the primary tumor, lymph node metastasis, distant metastasis classifications as well as the clinical staging in breast cancer patients." (PMID 23497677, 2013). "To address this issue, we examined for the first time the expression status of MACC1 in human breast cancer in this study." (PMID 23497677, 2013). "In conclusion, this is the first study aimed at evaluating the possibility of using MACC1 as a clinically relevant indicator for breast cancer recurrence and as a prognostic marker for patient survival in breast cancer." (PMID 23497677, 2013). "Stratification of breast cancer patients according to the estrogen receptor (ER) status revealed that MACC1 was prognostic for both ER-negative and ER-positive patients." (PMID 23497677, 2013). "We next examined the effectiveness of MACC1 expression in predicting overall survival of breast cancer patients." (PMID 23497677, 2013). "The IHC analysis showed that MACC1 staining was only marginally detectable in normal breast tissue, but in contrast, it was found dramatically overexpressed in breast cancer lesions." (PMID 23497677, 2013). "Finally, we also need to further elucidate the regulatory role of MACC1 in radiation-resistance breast cancer." (PMID 34221989, 2021). "In a word, our results showed high MACC1 expression is an unfavorable prognostic factor of patients with gynecologic cancers or breast cancer, and the MACC1 may be a potential therapeutic target of gynecologic cancers and breast cancer." (PMID 33663046, 2021). "Multivariate analysis suggested that MACC1 expression and the presence of lymphovascular invasion could be independent prognostic indicators for breast cancer (p = 0.015 and 0.042, respectively)." (PMID 34577857, 2021). "Therefore, further studies are recommended to include immune checkpoint markers and focus on the relationship between MACC1 expression and breast cancer subtypes." (PMID 34577857, 2021). "Up to 2020, there was 9 articles showed MACC1 might serve as a good biomarker for breast cancer, and our result keeps consistency with previously reported." (PMID 34221989, 2021). "The expression of MACC-1 in breast cancer and its correlation with outcomes is little known." (PMID 33400729, 2020). "Moreover, serum MACC1 exhibited significant prognostic value in breast cancer (AUC = 0.757, 95% CI: 0.700–0.814), and high MACC1 was associated with poor disease-free survival (HR 5.63, 95% CI: 3.51–9.04; P < 0.001)." (PMID 27793048, 2016). "MACC1 may represent a potentially useful biomarker for the prognosis of breast cancer patients and might be involved in progression of breast cancer." (PMID 23497677, 2013). "Likewise, MACC1 was an independent prognostic factor for overall survival in breast cancer when a multivariate Cox regression analysis was used in cohort 2 (P = 0.001, Hazard ratio: 3.190, 95% CI, 1.651 to 6.163)." (PMID 23497677, 2013). "Furthermore, a multivariate Cox regression analysis showed that after adjustment of tumor size and lymph node status, MACC1 was an independent prognostic factor for RFS in breast cancer (P = 0.006, Hazard ratio: 2.378, 95% CI, and 1.279 to 4.424)." (PMID 23497677, 2013). "Interestingly, while the expression level of MACC1 correlates with the N classification in breast cancer, it is also of prognostic value in both LN-positive and -negative patients." (PMID 23497677, 2013). "In order to determine whether MACC1 is clinically correlated with breast cancer progression, the expression of MACC1 was examined by IHC in two large cohorts of breast cancer patients." (PMID 23497677, 2013).
breast carcinoma (continued). "In our current study, two large independent patient cohorts were employed, with which not only was overexpression of MACC1 in breast cancer identified and validated, but also its correlations with clinical staging, distant metastasis and patient survival were established." (PMID 23497677, 2013). "More importantly, our study also strongly suggests that MACC1 might be an independent biomarker for the prediction of progression and prognosis of breast cancer." (PMID 23497677, 2013). "Taken together, our results suggest that MACC1 might represent a novel and potentially useful independent biomarker for the prognosis of patients with breast cancer." (PMID 23497677, 2013). "MACC1 may influence infiltration of the immune cells in the tumor microenvironment, enhance immune escape of tumor cells, and may serve as a reliable independent prognostic factor for breast cancer." (PMID 34577857, 2021). "Therefore, MACC1 expression can predict the prognosis of gynecologic cancers and breast cancer." (PMID 33663046, 2021). "In addition, MACC1 expression status may be useful for evaluating the effectiveness of novel anti-breast cancer therapeutic strategies and for developing rational criteria for the selection of treatments." (PMID 23497677, 2013). "However, the expression level of MACC1 in breast cancer and its correlation with the clinical outcome of the disease is unknown." (PMID 23497677, 2013). "Finally, to increase the power of the analysis, we pooled two prognostic datasets and examined whether the MACC1 was an independent prognostic factor for overall survival in ER+ as well as ER- breast cancer patients." (PMID 23497677, 2013). "Previous studies reported that high MACC1 expression increases the proliferation and viability of a wide range of tumor types, including CRC and breast cancer." (PMID 36432477, 2022). "We find that high MACC1 expression is significantly related to reduced RFS and overall survival of breast cancer patients." (PMID 23497677, 2013). "The finding that MACC1 expression has prognostic values in both ER-positive and -negative breast cancer subgroups warrants further evaluation to explore whether the biomarker can be clinically useful in the decision-making process for the treatment of breast cancer patients." (PMID 23497677, 2013). "Hence, our finding that MACC1 overexpression is closely related to the clinical outcome of breast cancer warrants further and in-depth investigation on whether and how MACC1 interacts with the HGF-c-MET pathway, or other signaling pathways, in this highly prevalent malignancy." (PMID 23497677, 2013). "Taken as a whole, the expression of MACC1 was positively correlated with clinical staging and TNM classification of breast cancer." (PMID 23497677, 2013). "MACC1 mRNA was identified using quantitative reverse transcription polymerase chain reaction in 120 breast cancer specimens and adjacent non-cancerous tissues." (PMID 34577857, 2021). "As shown in Figurer1A, protein levels of MACC1 were differentially upregulated in all 8 breast cancer samples as compared with their matched adjacent non-tumor tissue specimens." (PMID 23497677, 2013). "Because ER-positive and -negative breast cancers are considered to be two clinically as well as biologically different disease entities, we then separately investigated the prognostic value of MACC1 expression in these tumor subtypes." (PMID 23497677, 2013). "For the relapse-free survival curves shown in ER- breast cancer patients, although the survival curve for MACC1 high-expression patients lied marginally below that for the MACC1 low-expression group, the difference was not statistically significant (P = 0.286)." (PMID 23497677, 2013).
cervical cancer (18 papers, 2015 to 2024). A primary or metastatic malignant neoplasm involving the cervix. "Cervical cancer patients presenting genotype GG in MACC1 SNP rs975263 tended to have more risk to develop vaginal invasion than those with AA/AG." (PMID 32174779, 2020). "Cervical cancer patients with variant homozygote GG in MACC1 rs975263 tended to have vaginal invasion, as compared to those with AA/AG." (PMID 32174779, 2020). "Patient with cervical cancer exhibiting genotype GG in MACC1 SNP rs975263 tended to exert more risk to have vaginal invasion than those with AA/AG (p=0.042, OR: 8.70, 95% CI: 0.81-433.22)." (PMID 32174779, 2020). "In the meantime, cervical cancer patients with genotype GG in MACC1 SNP rs975263 tended to display more risk to have vaginal invasion than those with AA/AG (p=0.042, OR: 8.70, 95% CI: 0.81-433.22)." (PMID 32174779, 2020). "Therefore, we related the associations of MACC1 SNPs and clinicopathological characteristics with prognosis of cervical cancer patients, 5 years survival rate." (PMID 32174779, 2020). "In cervical cancer, MACC1 regulates the AKT/STAT3 signaling pathway to induce migration and invasion, but also cancer stemness." (PMID 38339354, 2024). "In cervical cancer, MACC1 has been described to induce not only migration and invasion via the Akt/STAT3 pathway, but also stemness as illustrated by sphere formation assays and the expression of stemness factors such as NANOG and Oct4." (PMID 39580452, 2024). "These processes were observed in cervical cancer downstream of MACC1, leading to induction of MMP2/9, functionally relevant for the degradation of the extracellular matrix and well-studied players in cancer metastasis." (PMID 39580452, 2024). "In cervical cancer, MACC1 induces migration, invasion, stemness, and the inhibition of apoptosis in cervical cancer cells by regulating the AKT pathway, and promotes cell invasion and angiogenesis." (PMID 36979146, 2023). "In this study, we investigated the role of MACC1 in cervical cancer on malignant biological behavior of tumor cells." (PMID 34939526, 2022). "Expressions of MACC1 were estimated by qRT-PCR, immunohistochemistry, and Western blot assays in cervical cancer tissues and cells." (PMID 34939526, 2022). "MiRNA-15a overexpression in vitro inhibited MACC1 expression and suppressed the proliferation of cervical cancer cells." (PMID 31137555, 2019). "In contrast, miRNA-15a knockdown experiments or absorption by HCP5 allowed increased MACC1 expression and the proliferation of cervical cancer cells." (PMID 31137555, 2019). "Moreover, in ovarian and cervical cancer, MACC1 increases the phosphorylation of MEK1/2 and ERK1/2, thereby increasing proliferation and suppressing cellular apoptosis." (PMID 39580452, 2024). "miR-877 was reduced and alleviated cell proliferation by MACC1 in cervical cancer." (PMID 35756697, 2022). "lncRNA HCP5 adjustable MACC1 triggers cervical cancer progression." (PMID 35602292, 2022). "Moreover, in cervical cancer, miR-338-3p regulates tumor cells growth in MACC1 through the MAPK signaling pathway." (PMID 34718336, 2021). "High expression of MACC1 was also found in lung 20, breast 21, ovarian 22 and cervical cancers." (PMID 32174779, 2020). "Meanwhile, cervical cancer patients with GG in MACC1 SNP rs975263 had 5 years survival rate 0.80 (95% CI=0.45-1.00) as compared to those with AA/AG 0.82 (95% CI=0.75-0.90) with no significantly different 5 years survival rate (p=0.897, HR=1.14, 95% CI=0.15-8.54)." (PMID 32174779, 2020). "In univariate analysis, cervical cancer patients with AG/GG in MACC1 SNP rs975263 had 5 years survival rate 0.89 (95% CI=0.79-0.99) as compared to those with AA 0.79 (95% CI=0.70-0.88) with no significantly different 5 years survival rate (p=0.195, HR=0.49, 95% CI=0.16-1.45)." (PMID 32174779, 2020). "As far as we know, no study investigates the associations of MACC1 SNPs with the development of cervical cancer and patient prognosis in Taiwanese women." (PMID 32174779, 2020).
cervical cancer (continued). "Furthermore, HCP5 and MACC1 were overexpressed in cervical cancer tissues compared to paracancerous tissue, and the survival rate of patients with cervical cancer was negatively correlated to HCP5 expression and positively correlated to miRNA-15a." (PMID 31137555, 2019). "Therefore, we conducted this study to investigate the involvement of the following 5 MACC1 SNPs rs975263, rs3095007, rs4721888, rs3735615 and rs1990172 in the development and clinicopathological characteristics of cervical cancer and patient prognosis in Taiwanese women." (PMID 32174779, 2020). "MACC1 has a comparable effect to miR-338-5p overexpression in suppressing the MAPK pathway, and miR-338-3p partially controls the expression of MACC1 in cervical cancer to influence the pathway’s negative regulation." (PMID 36979146, 2023). "For instance, miR-338-3p can promote angiogenesis in hepatocellular carcinoma (HCC) by targeting MACC1, b-catenin, and VEGF; MACC1 is positively correlated with VEGF in cholangiocarcinoma and angiogenesis in cervical cancer." (PMID 36979146, 2023). "Until now, no study investigates the involvement of MACC1 SNPs in the prognosis of cervical cancer patients." (PMID 32174779, 2020). "However, the impact of MACC1 SNPs on the development and clinical outcome of cervical cancer has not been explored yet." (PMID 32174779, 2020). "In conclusion, pelvic lymph node status rather than MACC1 SNPs was the only independent parameter that could significantly predict 5 years survival rate in Taiwanese women with cervical cancer." (PMID 32174779, 2020).
lymph node metastasis (18 papers, 2012 to 2025). "Our findings demonstrate that urothelial cancer patients with MACC1 (rs3095007) CA and AA genotypes have a lower risk of advanced T stage and lymph node metastasis." (PMID 38021160, 2023). "In conclusion, our findings demonstrate that urothelial cancer patients with MACC1 (rs3095007) CA and AA genotypes have a lower risk of advanced T stage and lymph node metastasis." (PMID 38021160, 2023). "After trisecting the age, we found that the level of MACC1 expression was only associated with lymph node metastasis in middle group patients aged 64–75." (PMID 34343214, 2021). "After adjustment for all variables and age stratification, MACC1 expression was found to be an independent risk factor for lymph node metastasis in the middle-aged group (OR 2.1, 95%CI 1.1–4.0)." (PMID 34343214, 2021). "Together, our meta-analysis showed that MACC1 overexpression was significantly associated with poor survival rates, regional invasion and lymph-node metastasis." (PMID 27542234, 2016). "High MACC1 expression was associated with advanced International Federation of Obstetricians and Gynecologists stage, poor differentiation and lymph node metastasis." (PMID 25009663, 2014). "The expression of MACC1 was significantly different in lymph node metastasis group (χ2 = 13.080, P < .001)." (PMID 41239615, 2025). "According to statistical analysis, MACC1 expression was substantially correlated with the main tumor, lymph node metastases, distant metastatic classification, and clinical staging in BC patients but not with age, ER and PR status, or HER2 status." (PMID 36979146, 2023). "In this study, we analyzed the relationship between MACC1 expression and lymph node metastasis and the effect of related variables on the relationship." (PMID 34343214, 2021). "There were also significant differences between the expression of MACC1 and tumor grade (P = 0.009), size of tumor (P = 0.009), invasion of depth (P < 0.001), lymph node metastasis (LNM) (P < 0.001), and tumor-node-metastasis (TNM) (P < 0.001)." (PMID 27793161, 2016). "In conclusion, we found that MACC1 expression indicated poor survival outcomes and regional invasion and lymph-node metastasis." (PMID 27542234, 2016). "We found that high levels of MACC1 often correlated with enhanced lymph node metastasis, distant metastasis and the clinicopathological stage." (PMID 24325214, 2013). "We analyzed the association of MACC1 polymorphisms with clinical data, including metachronous metastasis, UICC stages, tumor invasion, lymph node metastasis and patients’ survival (n = 154, stages I, II and III)." (PMID 22838389, 2012). "Interestingly, when stratifying age factors, We found that MACC1 expression had a correlation with lymph node metastasis only in the middle age group." (PMID 34343214, 2021). "Interestingly, in a previous study, a high level of MACC1 protein in the serum collected from pancreatic cancer patients has been detected and suggested to be correlated with lymph node metastasis, distant metastasis and a later TNM stage." (PMID 24949951, 2014). "Univariate analysis showed that patients with lymph node metastasis (p=0.008), advanced TNM stage (p<0.001), high YB-1 expression (p=0.004) and high MACC1 expression (p=0.044) had poorer survival outcomes." (PMID 28624808, 2017). "Multivariate COX regression analysis showed that the positive expression of KAI1, MACC1, and AGR2, TNM stage and lymph node metastasis stage in clinicopathological factors were independent prognostic factors for the OS time of patients with cervical squamous cell carcinoma (P < .05)." (PMID 41239615, 2025). "The expression of MACC1 was significantly upregulated in primary lesions in patients with lymph node metastasis compared with patients without lymph node metastasis in the 64–75 age group." (PMID 34343214, 2021).
lymph node metastasis (continued). "MACC1, vimentin, and E-cadherin protein levels in NPC tissues were significantly correlated with T stage (p=0.011), N stage (which is synonymous with lymph node metastasis; p=0.013, 0.011, 0.001, respectively), and cancer stages I to IV (p=0.023, 0.037, 0.022, respectively)." (PMID 33854976, 2021). "It was found that MACC1 protein expression was higher in primary foci with lymph node metastasis than in primary foci without lymph node metastasis in the 64–75 age group." (PMID 34343214, 2021). "Additionally, MACC1 expression was related to TNM stage (p<0.001), T state (p=0.033) and lymph node metastasis (p<0.001)." (PMID 28624808, 2017). "Furthermore, serum MACC1 levels were higher in patients with lymph node metastases compared to those without lymph node metastases (56.34 ± 15.53 pg/mL, 49.74 ± 15.60 pg/mL, respectively; P < 0.0001)." (PMID 27793048, 2016). "We speculate that MACC1 may not linearly relate to lymph node metastasis." (PMID 34343214, 2021).